TNF (tumor necrosis factor)
Diseases named in the same sentence as TNF in open-access papers (continued):
Sharing a sentence is not in itself a finding about the gene and the disease.
infection (continued). "Additionally, the kinetics of viral clearance in the lungs of TNF-/- OT-I recipients was similar to those that received WT cells, such that both mice eliminated the virus between days 6 and 9, as previously reported for non-transgenic models of this infection." (PMID 23874808, 2013). "Additionally, we could not detect any significant increased production of IFN-γ, TNF-α, or other Th1 types of cytokines in liver or spleen homogenate among all groups at day three after infection." (PMID 24049654, 2012). "Thus, high TNF mRNA values in transgenic regions could have protected neurons even in case of BDV-infection since no notable neuronal necrosis was detected in any of these areas despite strong inflammatory lesions." (PMID 22848506, 2012). "However, whether CD8 T cells are directly producing this TNFα in response to infection has not been tested." (PMID 21687650, 2011). "The lack of excessive TNF-alpha induction in AM after infection with the HPAIV H5N1 strain used in this study might indicate that, in contrast to previous conclusions based on studies with MM, the AM does not contribute to the excessive immune response after HPAIV H5N1 infections." (PMID 21731493, 2011). "Interestingly, for TNF-αactivation was largely independent of productive infection, a finding that also indicates that induction of IL-6 and IL-10 are not being induced as a by-product of TNF-α up-regulation, but rather that these mediators are independently induced." (PMID 21572983, 2011). "Neither SOD-1 nor TNF-alpha could differentiate between the infections." (PMID 20386593, 2010). "Finally, they represented diverse molecular classes – cytokines (TNF, IL-12p40, IL-6, IL-10, GM-CSF), chemokines (RANTES, MCP-1), enzymes (iNOS, cyclooxygenase [COX] 2) and cell-surface co-stimulatory proteins (Delta-4, CD40, GITRL) – with known roles in immune responses to infection." (PMID 21170273, 2010). "In addition to the evidence that peripherally immune-derived cytokines can trigger neuro-endocrine responses during infection and inflammation, several non-immune functions of cytokines such as TNFα, IL-1β and IL-6 synthesised within the CNS in the absence of disease have been described." (PMID 19254758, 2009). "However, TNFα is a key cytokine in protective host defence against Mycobacterium tuberculosis (M. tuberculosis) and, together with TNF-dependent chemokines play an important role in the development and maintenance of the granuloma which compartmentalises tubercle bacilli during infection." (PMID 18706526, 2008). "Here we have shown that after infection of non-vaccinated Tlr4-deficient mice the number of bacteria, and lung IL-1α and IL-1β expression are higher than in similarly treated wild-type controls, while bronchial LN cell IFN-γ and IL-17 production and splenocyte TNF-α production are lower." (PMID 18498620, 2008). "Therefore in the absence of cFLAR induction, and in conjunction with the observed TNF-α production, we hypothesize that infection in the absence of pXO1 probably induces apoptosis through a classical extrinsic TNF-α receptor-mediated caspase-8 pathway." (PMID 19014542, 2008). "However, TNF-α was still expressed in TLR2-/- cells at approximately 50% of the level seen in wild-type cells, and it is possible that immune mediators such as TNF-α produced early in infection, might induce apoptosis." (PMID 17470292, 2007). "Thus, while we demonstrate that pre-infection of host cells with an effector delivery-defective mutant had no significant impact on the ability of TNFα to activate these pathways, cells pre-infected for 3 h with effector delivery-competent strains were effectively unresponsive to this cytokine." (PMID 17388785, 2007).
infection (continued). "This lack of activation of the HIV-1 replication with TNF-α contrasts with the results obtained with choriocarcinoma cell lines by Vidricaire and colleagues who reported an increase of luciferase activity in these cells after infection with R5 or X4-Env pseudotyped HIV-1 in the presence of TNF-α." (PMID 16796744, 2006). "gonorrhoeae strain MS11mkC, we did not see similar increases in urine IL-6, TNF-α, or IL-1β, although differences in IL-6, TNF-α were observed in participants with later development of infection." (PMID 41810365, 2026). "Serum levels of TNF-α, IL-6, and IFN-γ were significantly higher in the infection group than in the non-infection group (P<0.05)." (PMID 40677522, 2025). "The results of this study indicate that serum levels of TNF-α, IL-6, and IFN-γ were significantly elevated in DFI patients compared to diabetic foot patients without infection, and their levels positively correlated with infection severity." (PMID 40677522, 2025). "Inflammation is characterized by an increase in pro-inflammatory cytokines interleukin 1 β (IL-1β), interleukin 6 (IL-6), and tumor necrosis factor-α (TNF-α), even in the absence of overt infection or injury." (PMID 40509402, 2025). "There was no significant alterations in production of TNF, granzyme B (GZMB), or perforin between adult or aged animals irrespective of infection status." (PMID 39550693, 2025). "Despite high NPV (88%), TNF-α—like IL-6 (NPV = 82%) and IL-8 (NPV = 88%)—failed to differentiate infection severity (p > 0.05 for all)." (PMID 40647525, 2025). "Although the expression of CCL2, CCL5 and TNF was not as robust as IFN-β, there was a pattern of activation after infection, which was mildly inhibited by G140 for CCL2 and CCL5." (PMID 41139159, 2025). "We did not observe a notable release of TNF-α, but all three FSSC species induced a higher release of IL-6 and IL-8 from infected hemi-cornea models than C. albicans, especially after 48 h of infection." (PMID 41186402, 2025). "infection did not change the levels of cytokines interleukin 1β (IL-1β), IL-6, IL-10, interferon gamma (IFN-γ), and tumor necrosis factor alpha (TNF-α)." (PMID 40302747, 2025). "Despite neither strain significantly altering NF-κB or TNFα expression, both are major inflammatory mediators, BR15 infection resulted in elevated levels of both pro- and anti-inflammatory cytokines." (PMID 40732762, 2025). "Infection of THP-1 cells with F. novicida WT, wbtF mutant, and the complemented strain produced similar TNF-α and IL-6 responses, indicating that wbtF does not significantly affect cytokine production." (PMID 41141590, 2025). "A prior study reported the upregulation of IL-1β, IL-8, TNF-α, and IFN-γ in the kidneys of rainbow trout fed TC at the dose of 250 mg/kg for 60 days in the absence of infection." (PMID 38668265, 2024). "Despite the lack of viral titer in the human astrocytes, the infection with H7N9 promoted an increased expression of pro-inflammatory cytokines, such as TNF-α, IL-6, IL-8, CCL2, and IFN-β 24 hpi." (PMID 39203555, 2024). "Consequently, vaccine strategies emphasizing the stimulation of IFN-γ and TNF-α, which appear necessary for salivary gland CMV control, rather than simply a robust CD8 T cell response, may emerge as essential requirements for preventing or mitigating the duration and severity of infection." (PMID 39150988, 2024). "Compared with the control group, the contents of PCT, TNF‐α, and IL‐6 were higher was lower in the DFU infection control group without significant difference (p > .05)." (PMID 38577990, 2024). "For example, diabetic mice infected with Porphyromonas gingivalis exhibit elevated TNF, MIP-2, and MCP-1 levels 3 days post-infection compared with non-diabetic controls." (PMID 38526063, 2024). "In line with current results denying any infection-driven increase of endothelial EV release, treatments of HUVEC with TNF-α did not affect the production, size or morphology of EVs." (PMID 39749330, 2024).
infection (continued). "This notion of the baseline infection state influencing HIV-1 control is not unprecedented; for instance, TNF-a expression was documented to display a negative correlation with the HIV-1 latent reservoir in a recent cohort of individuals with HIV." (PMID 39555417, 2024). "Non-immunized animals displayed an increase in IFN-γ, TNF, IL-6 and IL-12 after inoculation with EHDV-8, with an important and significant increase at day 5 post-infection compared to the immunized group." (PMID 38904031, 2024). "In our study on the early infection phase of FHV-1, the upregulation of CCL17, CCL20, and CXCL10 among these cytokines and chemokines, as well as that of TNF were observed, while there were no significant changes in IFNs." (PMID 39591303, 2024). "Six months after chemotherapy, the Th1:Th2 ratio increased and MTB specific IFN-γ and TNF-α producing CD4+ T cells were detected, but all of these remained lower than in children without Sh infection." (PMID 39250522, 2024). "However, although mRNA level of TNF-α was remarkably upregulated, the production of TNF-α was only detectable at 24 h post-infection (hpi) at low level (20 pg/mL, data not shown), which may be due to the TNF-α production mainly from activated immune cell types, such as macrophages." (PMID 39104852, 2024). "We also tested TNF, IL-1β and IL-6 in BALF under homeostasis and observed no significant changes, though they began to trend higher on day 10 post-infection in ECSparcl1-OE mice." (PMID 38762489, 2024). "Exhausted T cells in concert with TNF-α and IFN-γ, are capable of driving non-specific immune responses in order to prolong the infection." (PMID 37163092, 2023). "At 4 weeks post infection both groups produced increased levels of IFN-γ, IL-4, IL-10, and TNF-α from splenic cells that were not statistically different between the groups, however, the trend was for higher mean levels in the WT-inoculated animals." (PMID 37185599, 2023). "The infection with T. cruzi in Blimp-1-deficient mice triggered a robust pro-inflammatory response, evidenced by high levels of cytokines such as TNF and IFN-γ, both locally and systemically on day 12 post-infection, but not earlier." (PMID 37908369, 2023). "infections as the absence of TNF receptor 2 (TNFR2) and/or administration of TNFα-neutralizing antibodies leads to an absence of cerebral malaria and fewer liver lesions." (PMID 37375100, 2023). "Compared to infection without rAb-ADA, the co-administration of DENV-2 and rAb-ADA resulted in a substantial increase of inflammatory mediator genes IL-1β, IL-6, TNF-α, and CCL2 in Raw264.7 and THP-1 cells." (PMID 37794048, 2023). "Exhausted T cells along with TNF-α, and IFN-γ induce non-specific immune responses aiding in retaining the infection." (PMID 37163092, 2023). "We showed that in response to B. pertussis, higher transcript levels of TNF, IL-1β, IL-6 and MIP-2α were detected 6 hours after infection when MPI were cultured without GM-CSF and therefore when STAT5 is inactivated." (PMID 37841236, 2023). "Hence, locally produced pro-inflammatory cytokines such as tumor necrosis factor alpha (TNFα), interleukins (IL)-1, or IL-6 and prostaglandin E2 (PGE2) could move via systemic circulation to distant organs and contribute to cellular dysbalance far away from the side of infection." (PMID 37736098, 2023). "In comparison with control, non-treated mice, blocking IDO produced a decrease of bacilli burdens at day 60 post-infection, without significant difference in IFN-γ, TNF-α, and IL-4 expression." (PMID 37284503, 2023). "Because MSCl cells did not produce pro-inflammatory TNFα and IL-1β upon L. casei CFS treatment in our experimental system, we decided to use the MSC cell line in our further viral-infection-mimicking experiments." (PMID 37371616, 2023). "After infection with SARS-CoV-2, cells from patients with AUD had a robust inflammatory response, including higher levels of TNFα, IL-1β, and IFNγ secreted than infected non-AUD cells." (PMID 37786945, 2023).
infection (continued). "In a non-inflammatory setting (low levels of TNF-α and IFN-γ), bone marrow MSCs adopt a pro-inflammatory phenotype and enhance T lymphocyte response by secreting chemokines to recruit lymphocytes for infection." (PMID 38124750, 2023). "At 4 weeks post-infection, we observed a significant increase in lung infiltrating IL-2, IFN-γ, TNF-α, and IL-17 secreting CD4 but not CD8 T cells in the vaccinated group." (PMID 37359562, 2023). "In two of three primary cell isolates, TNF-α was not expressed at baseline, but in one isolate, strong induction was seen following Mon601 infection and a modest induction after EHI0578Y05 infection." (PMID 37515098, 2023). "Although many potential biomarkers of infection have been studied, for example interleukin-6 (IL-6), interleukin-8 (IL-8), interferon gamma (TNF-α) and tumor necrosis factor alpha (TNF-β), satisfactory results have still not been obtained." (PMID 36670590, 2022). "Overall, the majority of cytokines (including IL-6 and TNF-α, key inflammatory cytokines) in the 48-plex assay were not significantly altered by butyrate or PCI 34,051, either alone or in combination with infection." (PMID 36144424, 2022). "Bannerman found a significant increase in IL-1β levels in milk after S. aureus infection, while TNF-α levels did not change, so the authors suggested that the limited cytokine response to S. aureus may contribute to the well-known ability of the bacterium to establish chronic intramammary infection." (PMID 35624447, 2022). "The concentration of the cytokines TNF-α and IFN-γ (Th1) was higher in the infected animals (p < 0.05) compared to the controls (without infection), and this increase was much more marked in the Il17a−/− mice than in wild C57BL/6J mice (infected)." (PMID 35208830, 2022). "The infection induced by S. aureus significantly increased the production c IL-6, MCP-1, TNF-α, and VEGF in relation to the lesions without infection (p < 0.001); for other markers, no conclusive results were obtained." (PMID 36422571, 2022). "Further studies need to be done in vivo to evaluate the effectiveness of partial TNF-α and IFN-γ restoration by supplementation in clearing infection rather than exclusively to maintain the granuloma." (PMID 36159650, 2022). "Infection of hyperpigmented hemolytic GBS in non-human primate model increased the levels of cytokines like IL-1β, tumor necrosis factor-α (TNF-α), IL-6, and IL-8 in amniotic fluid." (PMID 35794927, 2022). "Albeit the differences were small, infection-induced transcripts for COX-1, mPGES-1, and TNF-α appeared to be somewhat higher in the absence of IL-1α/β." (PMID 35523455, 2022). "Previous studies reported that TNF-α modulation is PEDV strain dependent, and its infection does not have a detectable effect on IL6 gene modulation in the small intestine by 5 DPI12." (PMID 36376395, 2022). "IL-4, IL-10, and TNF-α levels were not influenced by the SA-11 and EDIM infections in the DRI group, but the B-GOS significantly induced higher levels than REF and/or DRI groups (p < 0.05)." (PMID 35626706, 2022). "None of the cytokines (IL-1β, TNF and IFNγ) were able to prevent the reduction in TEER upon infection with B. pertussis (data not shown)." (PMID 35256671, 2022). "IL-1β, TNF-α, CXCL1, and CXCL2 were significantly decreased in fibrotic mice compared with nonfibrotic mice after infection, both at the protein and mRNA levels." (PMID 34990413, 2022). "In the UK study, the MCP-1 levels did not change, and only TNF-α and CXCL10 increased in the infection-primed subjects at 6 days post-vaccination, suggesting a potential polarization towards a Th1 phenotype." (PMID 36119038, 2022). "In this systematic review, we summarize results from 20 anti-TNF-α de-escalation studies (14 RCTs and 6 non-RCTS) on the reduction in infections and skin manifestation." (PMID 35625771, 2022).
infection (continued). "In contrast, moM1 infection with virulent 22653/14 ASFV did not induce the release of either proinflammatory (IL-1α, IL-1β, IL-6, TNF-α) or anti-inflammatory (IL-10) or pro-Th1 (IL-12, IL-18) cytokines." (PMID 35215216, 2022). "Other cytokines, namely TNF-α, IFN-γ, CCL2, and TGF-β, showed no significant changes following the polymicrobial infection or nisin treatment, although the anti-inflammatory cytokine TGF-β showed a trend toward higher levels with nisin treatment." (PMID 35672331, 2022). "In this case, the frequency of cells producing TNF-α slightly increased, and IL-10 or TGF-β1 were not the prevalent cytokines produced after infection." (PMID 35720410, 2022). "Our results show that IL-4, IL-6, IL-8, IL-10, IL-12P70, IL-1β, IL-2, IFN-γ, TNF-α, TNF-β and IL-17A are in the lungs The expression level of bacterially infected individuals was higher than that of patients without any infections (P<0.05)." (PMID 34925324, 2021). "While ADE for FcR bearing cells was observed, longer term infection was abortive, and the post-ADE mRNA expression profiles for IFN-α/β, MCP-1, IP-10, TNF, MIP-1 were not altered." (PMID 33842517, 2021). "Low levels of human IL‐1β and TNF‐α were recovered from WT, LVS, and clcA mutant infection supernatants, but were not considered physiologically relevant (<10 pg/ml for all strains, Figure A6E‐F)." (PMID 33970545, 2021). "Studies in humans reveal that infection with DENV reduces both the number and frequency of non-classical CD14+CD16++ monocytes, which produce TNF and show a more activated phenotype than cells from healthy controls." (PMID 33829283, 2021). "There was prominent induction of IL-6, CCL3, and CCL4 in genotype 1 infected decidua and placenta compared to genotype 3 while expression of TNF-α, IL-15, IL-18, and CCL-5 was barely detected regardless of infection." (PMID 34502167, 2021). "Significantly higher levels of IL-17, IL-1β, IL-6 and TNF-α were detected in BAL and lung tissue lysates from infected CS-exposed mice, compared to non-infected animals at 24h after infection." (PMID 33784296, 2021). "However, there were no significant changes in serum IL-6, TNF-α, and IL-1β levels under the same condition; moreover, we did not observe any reductions in damage to the lungs and kidneys (organs that are vulnerable to severe infection) in CdCl3-pretreated mice after CLP." (PMID 33564275, 2021). "We also observed that the inflammatory biomarkers CRP, IL6 and TNF-α were higher among patients who developed AKI compared to those who did not, which highlights the role of severe infection in the pathogenesis of AKI." (PMID 34577543, 2021). "Conversely, IL-17A, TNF-α, and IFN-γ secretion were strongly induced in the colon of CR-infected mice compared to non-infected mice at day 10 of infection." (PMID 33654214, 2021). "In contrast, chronic CS exposure (>2 weeks) results in exaggerated cytokine responses (TNF-α, IFN-y, IL-6, IL-12, IL-23, IL-1, IL-5, IL-10, KC, MIP-1a, IL-17, IL-1B) with infection compared to non-smoking infected controls." (PMID 34959590, 2021). "In contrast, KO of TLR9 did not change the production of either IL-6 or TNFα, indicating that, in human macrophages, TLR9 is not a relevant or important receptor during the early stages of intracellular infection." (PMID 34280250, 2021). "All other markers (CCL4, IL-1Ra, TNF, S100A12, ferritin, C1q, CRP, and ApoA1) yielded no or hardly any detectable signals or failed to discriminate before and after infection (ApoA1, C1q)." (PMID 34943175, 2021). "Evidence supporting this can be seen in a study of 73 critically ill patients in whom ex vivo LPS-induced TNF-alpha production was measured and found to be similar patients who did and those who did not develop an ICU-acquired infection." (PMID 34945111, 2021).